LEP (leptin)
Diseases named in the same sentence as LEP in open-access papers (continued):
Sharing a sentence is not in itself a finding about the gene and the disease.
Obesity (continued). "DEHP and obesity reduced sperm count and motility, relative testis and epididymis weight, and testosterone level but increased the levels of MDA, H2O2, leptin, and estradiol." (PMID 29887939, 2018). "The main objective of the present study was to investigate the effects of obesity and short-term (8 weeks) SPI consumption on body weight, energy intake, liver steatosis, and serum AST, ALT, and leptin levels in female Zucker rats." (PMID 29757972, 2018). "Thus, obesity per se can act synergistically with maternal obesity to further increase circulating insulin and leptin levels, which may contribute to hypertension risk but not to additional loss of cardiac function." (PMID 29635288, 2018). "Several of the observed DMCs were located in genes related to T2D or obesity, such as ALOX12, PAMR1, and GNAS in WB; IRS1, LEP, and ADIPOQ in SAT; LCAT, FOXA2, KCNQ1, and GCKR in VAT; and PKD4, HNF4A, XBP1, and PON1 in LT." (PMID 29466957, 2018). "It has been shown that, in tissue samples, expression of LEP was higher while expression of ADIPOQ was lower in lipoma compared to normal adipose tissue, which is the expression pattern characteristic for obesity." (PMID 30544806, 2018). "Unpublished mRNA data; from our laboratory indicate increased mRNA expression levels for leptin in the fat pad and synovium of rats with DIO compared to those on a chow diet, after a 12-week obesity induction period." (PMID 29527173, 2018). "This is in agreement with elevated hypothalamic pSTAT3 in obesity and the fact that LEPR antagonism increases food intake and body-weight equally in lean and DIO mice – despite differences in exogenous leptin sensitivity." (PMID 29748097, 2018). "The reduction of leptin and induction of adiponectin in the study also indicated that GTE modulated obesity in rats." (PMID 28804438, 2017). "This group had a phenotype typical of diet‐induced obesity (DIO), with increased total caloric intake, body weight gain, body fat mass and blood leptin concentrations." (PMID 28653356, 2017). "Like leptin, expression of the pro-inflammatory chemokine MCP-1 is upregulated in PVAT in obesity, and MCP-1 also promotes VSMC proliferation." (PMID 29234289, 2017). "Diet-induced obesity and the leptin treatment up-regulated PTPRJ expression in the hypothalamus, while the overexpression of PTPRJ induced leptin resistance." (PMID 28912580, 2017). "Our results for leptin and PAI-1 are similar to other reports that LSG leads to significant reductions of both markers of obesity." (PMID 27465935, 2017). "Leptin contributes to the inflammatory state in obesity by modulating TNF-α and activating macrophages, and butyrate reduced leptin levels in mid-adult and late-adult mice." (PMID 28686216, 2017). "This variation in the secretion of adipocytokines by the adipose deposits may explain the relationship between obesity and the development of breast cancer, since obese subjects present a decrease in the levels of circulating adiponectin and increase in the plasmatic concentration of leptin." (PMID 29311755, 2017). "PTP1B-null mice are resistant to weight gain induced by high-fat diet (HFD) or by deletion of the leptin gene, suggesting PTP1B inhibition as a strategy to rescue leptin signaling in food intake disorders and obesity." (PMID 28197094, 2017). "In obesity, increased blood levels of free fatty acids (FFA), tumor necrosis factor alpha (TNF-alpha) and leptin have been demonstrated to contribute to the development of type 2 diabetes." (PMID 29209160, 2017). "Overweight and obesity are generally believed to be protective factors for BMD through mechanical loading and hormonal factors, including insulin, estrogen, and leptin." (PMID 28253896, 2017). "Accordingly, adipocyte-derived leptin and FFA, both of which are increased in obesity, have been shown to enhance Th1 proliferation and/or IFN-γ production." (PMID 29186929, 2017).
Obesity (continued). "Three genes were chosen because they are important regulators of biological pathways involved in obesity: CRH (stress), ICAM-1 (inflammation), and LEP (appetite)." (PMID 28360946, 2017). "Two adipokines, adiponectin (ADIPO), and leptin (LEP), are altered with obesity and exert antagonistic effects on breast cancer proliferation." (PMID 28676553, 2017). "As is well known, leptin plays an important role in the relationship of LEP G2548A and LEPR Q223R with obesity, diabetes mellitus, dyslipidemia and CK." (PMID 29296187, 2017). "Considering the pleiotropic role of leptin in energy balance, the administration of commensal bacteria able to regulate its secretion and function could be an attractive strategy for the management of malnutrition (undernutrition and obesity), but appropriate strains need to be selected." (PMID 28348560, 2017). "Using a combination of mouse genetics, electrophysiology, optogenetics and DREADD, our results demonstrate an importance of VMAT2-mediated neurotransmission in mediating the leptin action on HFD feeding and diet-induced obesity." (PMID 28560316, 2017). "However, further studies of the integrity of the BACHD rats’ leptin system are unlikely to offer any final conclusions regarding whether or not their motivational deficit is caused by their obesity." (PMID 28273120, 2017). "We studied the longitudinal effects of long term HFD exposure on DNA methylation of the Leptin and Pparg2 promoters in two fat depots, GAT and SAT, in adult mice during the development of obesity." (PMID 28256596, 2017). "Thus, individuals with LEPR-positive cancers could be particularly susceptible to high leptin levels seen in obesity irrespective of LEP expression in the tumor itself." (PMID 29212170, 2017). "It is well known that AT endocrine dysfunction associated to obesity is closely related to adipocyte size, rather than to pad mass, and hypertrophic adipocytes are characterized by impaired insulin sensitivity and changes in the adipokine secretory pattern, including higher leptin production." (PMID 27011203, 2016). "In contrast, VMH lesions tend to destroy the downstream targets of leptin action and leave the actions of the LHA unopposed, generating obesity." (PMID 26819774, 2016). "CRTC 1 regulates leptin expression in the hypothalamus, CRTC 2 triggers gluconeogenesis in the liver, which drives insulin resistance and preludes obesity." (PMID 27596982, 2016). "We took forward the genome-wide significant leptin loci near LEP, nearSLC32A1, in GCKR and near CCNL1, to examine theirassociations with obesity-related and metabolic traits and to more directlyassess their putative roles in the control of circulating leptin." (PMID 26833098, 2016). "Obesity contributes to immune dysfunction by secretion of inflammatory adipokines from adipose tissues such as TNF-α, IL-6, and leptin." (PMID 27703805, 2016). "The association between Lequesne index and leptin was highly increased in the two models when the effect of leptin was not controlled by anthropometric or inflammatory variables, indicating that the pathway of leptin in clinical severity could be shared by TNF-α and obesity." (PMID 27629533, 2016). "Moreover, it has been proposed that metabolic factors, including inflamed adipose tissue, dyslipidemia, oxidative stress, endothelial dysfunction and leptin dysregulation, as well as the clustering of these factors in metabolic syndrome, may play a crucial role in obesity-induced OA." (PMID 27677265, 2016). "Before the onset of obesity, young AC3−/− mice (2 months) exhibit reduced physical activity, increased food consumption, and leptin insensitivity." (PMID 27942392, 2016). "This supports the harmful role of leptin and meaningful regulator role of SOCS-3 in obesity-related OA." (PMID 27716333, 2016).
Obesity (continued). "Leptin is an anti-obesity hormone that inhibits food intake and increases energy metabolism, and, as such, treatments involving leptin were expected to be beneficial for obesity; however, since most obese patients are in a state of leptin resistance, these treatments may not be useful." (PMID 27375555, 2016). "Since we have found that both insulin and leptin increase Sam68 expression in breast cancer cell lines, the hyperinsulinemia and hyperleptinemia that occur in obese women may contribute to the overexpression of Sam68 found in the tumours from patients with obesity-related breast cancer." (PMID 27415018, 2016). "Conversely, our study revealed that insulin can potentiate leptin-induced STAT3, a transcription factor critical to a major signaling pathway exerting anti-obesity effects of leptin." (PMID 27812350, 2016). "In the current study, we investigated leptin and IGF1 signaling due to our observation of increased obesity-related factors such as body weight, serum triglyceride and insulin, and peroxisome proliferator-activated receptor γ (PPARγ) after 56Fe radiation." (PMID 27558773, 2016). "Biochemical profiles of hormones involved in obesity including T4, T3, insulin growth factor (IGF), leptin, AGRP, ghrelin, and NPY were all measured at baseline and after LHA-DBS with no change following stimulation." (PMID 26819774, 2016). "We used HepG2 cells, primary neuronal cells and a high-fat diet (HFD)-induced obesity rat model to determine the effect of KBH-1 in vitro and in vivo on hepatic steatosis and leptin resistance accompanied by obesity." (PMID 27618865, 2016). "Furthermore, it has been reported that hypoxia-treated cells up-regulate obese (ob) gene transcription, suggesting that enhancement of leptin secretion in vivo under hypoxic conditions may be a mechanism to consider when developing therapeutic methods for obesity treatment." (PMID 27313541, 2016). "In accordance with the results of HFD-induced obesity in vivo, KBH-1 significantly up-regulated the activation of leptin-mediated signals, including AMPK and JAK2, in a time-dependent manner." (PMID 27618865, 2016). "Several adipokines, such as leptin, IGF 1, interleukin 6 (IL 6) and Vascular endothelial growth factor (VEGF), are increased in obesity." (PMID 25928422, 2015). "We report here that ADCY5 expression is strongly related to obesity and fat distribution, because both VAT and SAT ADCY5 correlate with body weight, BMI, % body fat, waist and hip circumferences, and leptin serum concentrations." (PMID 25793868, 2015). "It is also recognized that plasma leptin and CRP levels are upregulated in obesity and proinflammatory states and closely related." (PMID 25929254, 2015). "Moreover, adipokine imbalance, such as increased serum leptin levels and decreased serum adiponectin levels, is critically involved in obesity- and diabetes-related liver tumorigenesis, indicating that improving adipokine imbalance may be effective in preventing liver tumorigenesis." (PMID 25879666, 2015). "However, in the current study, the absence of β-adrenergic damage may be due to the hyperleptinemia caused by obesity; no studies have evaluated the resistance to leptin on the β-adrenergic system." (PMID 26390297, 2015). "The anti-obesity effect of TPEE is likely due to reduced expression of lipogenic genes such as FAS, SREBP-1c, PPARγ and leptin and up regulation of adiponectin and AMPK-1α." (PMID 25887331, 2015). "Furthermore, the biological activity of cytokines that are increased during placental ischemia should be examined and whether this activity is exaggerated by obesity or specific metabolic factors such as high levels of leptin, cholesterol, fatty acids, insulin or glucose." (PMID 26569331, 2015). "The purpose of this study was to determine if systemic leptin administration stimulated bone formation and preserved femoral head shape in INFH in rats with induced obesity." (PMID 25797953, 2015).
Obesity (continued). "To gain insight into these findings, we evaluated the impact of both factors, the body mass index as a representative of the obesity and the insulin resistance calculated by HOMA-IR in the current study by regression analysis on leptin and sOB-R levels." (PMID 26180527, 2015). "Moreover, the beneficial effects of AT1 receptor blockers on adipose tissue mass and insulin resistance in obesity could be related to the enhancement of adiponectin expression, the reduction of leptin expression, and the concomitant correction of the leptin/adiponectin imbalance." (PMID 26491235, 2015). "However, we must point out that this is not the only polymorphism in this region of the gene, which may act in combination with other polymorphisms and non-genetic factors such as exercise, thereby contributing to what is known as leptin resistance, and thus, increasing the obesity phenotype." (PMID 26365669, 2015). "However, it is possible that the association of obesity with BMD is based in the conversion of androgen to estrogen, which improves bone mass in both males and females and maintains healthy plasma levels of insulin and regulating factors such as insulin-like growth factor-1, leptin, and adiponectin." (PMID 26090818, 2015). "The adipokines adiponectin, leptin, TNF-α and adipocyte fatty acid-binding protein (AFABP) are increased in obesity and pregnancy and are prime candidates for direct involvement in the pathophysiology of GDM." (PMID 26110385, 2015). "Moreover, serum insulin is found to exhibit a significant positive correlation with BMI and leptin in both AMI and control subjects thereby suggesting that hyperleptinemia might be associated with the development of obesity and subsequent metabolic abnormalities such as hyperinsulinemia." (PMID 25762868, 2015). "Thus, leptin appeared to be an important contributor to hypertension that may accompany obesity." (PMID 26617526, 2015). "Obesity also affects the production of adiponectin (ADIPOQ), leptin and retinol binding protein 4 (RBP4)." (PMID 25938677, 2015). "The adipocyte-derived hormone, leptin, has emerged as an important regulator of regional sympathetic nerve activity (SNA) with pathophysiological implications in obesity." (PMID 26381017, 2015). "The ghrelin and leptin secretions are possibly dysregulated with HFD, impairing homeostasis and eventually promoting obesity." (PMID 25709707, 2015). "In summary, the results of this study demonstrated that systemic administration of leptin enhanced bone regeneration and preserved osteonecrotic femoral heads in rats with INFH and induced obesity through increasing vascularity and bone formation." (PMID 25797953, 2015). "Conversely, women afflicted with PCOS endure a state of hyperandrogenism which results in increased adiposity, leptin, inflammatory markers TNFα and IL6, and obesity independent decreases in adiponectin." (PMID 26317527, 2015). "To determine whether LEP and ADIPOQ epigenetic profiles are involved in the pathogenesis of obesity and cardiometabolic complications, we first assessed the associations between LEP and ADIPOQ DNA methylation levels in adipose tissues and blood and obesity-related anthropometric measures." (PMID 25929254, 2015). "Leptin, an adipokine produced in the liver and the adipose tissue, is thought to contribute, in part, to NASH development in obesity through its proinflammatory actions on sinusoidal epithelial cells and Kupffer cells." (PMID 25658689, 2015). "Furthermore, elevated leptin levels are correlated with production of vascular endothelial growth factor (VEGF) 10, leading to angiogenesis, which may lead to resistance to VEGF-targeted drugs, such as bevacizumab in obesity-associated cases." (PMID 26211512, 2015). "Hence, we hypothesised that polymorphisms in LEP and LEPR could lead to an increased risk for differentiated thyroid cancer (DTC), thus establishing the link between the observed epidemiological increases in both thyroid cancer and obesity rates." (PMID 25810718, 2015).
Obesity (continued). "The goal of this project was to determine the role of leptin in the PPN, and thus in obesity-related sleep disorders." (PMID 25368599, 2014). "Obesity-related cytokines, such as IL-6, TNF-α, as well as adiponectin, visfatin, and leptin play important roles in the development of NAFLD, causing ROS-mediated hepatocellular injury." (PMID 25548896, 2014). "Since converging evidence suggests that impaired leptin signaling may affect mood regulation and food reward perception in humans, impaired leptin signaling cascades may represent a biological mechanism binding obesity and depression, in particular when obesity is paired with compulsive overeating." (PMID 25386150, 2014). "Previously it has been demonstrated that in short-term obesity the NO-dependent and the EDHF-dependent components of vascular effect of leptin are impaired and up-regulated, respectively." (PMID 24475175, 2014). "Accumulating evidence suggests these changes are due to greater circulating concentrations of the adipokine leptin which strongly correlate with RSNA and MAP in animal models of obesity." (PMID 25520669, 2014). "Beyond the local production of leptin in EAT, there was also increased circulating leptin levels in obesity, metabolic syndrome, and IR state." (PMID 25383099, 2014). "Thus, in both settings loss of FTO protects against obesity independent of the presence of leptin." (PMID 25144618, 2014). "Considering notable reduction in circulating leptin levels and food intake in chow-fed lean mice after DT injection, we speculate that markedly increased inflammatory cytokine in circulation may cause robust hypothalamic inflammation independent of obesity-related leptin resistance." (PMID 24911652, 2014). "Our finding that a paradoxical decrease in circulating leptin occurs in patients with severe OSA deserves further studies in experimental and human models of obesity." (PMID 24982545, 2014). "So far, several genes, such as proopiomelanocortin (POMC), leptin receptor (LEPR), leptin (LEP), proconvertase 1 (PC1), and melanocortin 4 receptor (MC4R), have been confirmed as the casual genes to the onset of monogenic obesity." (PMID 24707501, 2014). "In later phase of obesity when insulin sensitivity is compromised, both NO- and EDHF-mimetic effects of leptin are impaired leading to unopposed stimulation of SNS and blood pressure elevation." (PMID 24475175, 2014). "We have identified four salivary biomarkers in 10-year old subjects that change significantly with increasing obesity; insulin, CRP, adiponectin and leptin." (PMID 24915044, 2014). "It remains unclear whether compositional changes in the gut microbiome of obese animals are due to altered leptin action resulting from hyperphagia, from physiologic changes associated with obesity, or from other leptin actions independent of food intake and adiposity." (PMID 24424041, 2014). "For several adipokines (ANGPTL3, DLL1, chemerin, clusterin, leptin, Nampt, resistin, GPX3), we identified a close relationship with parameters of obesity (BMI, waist circumference, body fat mass), but also inflammation (hsCrP)." (PMID 24968098, 2014). "The purpose of this study was to examine the role of phospholipase D1 (PLD1) in leptin-induced expression of the proinflammatory cytokine, tumor necrosis factor (TNF)-α, and to suggest a molecular link between obesity and respiratory tract inflammation." (PMID 25047119, 2014). "Indeed, an intact leptin-Notch axis could be involved in obesity-related breast cancer." (PMID 24716804, 2014). "Leptin (LEP) is a hormone secreted from adipocytes that plays an important role in energetic metabolism, control of food intake, and obesity through its binding to LEPR receptors." (PMID 26034683, 2014). "There are several studies indicating links of leptin gene (LEP) and leptin receptor gene (LEPR) variations with obesity, insulin resistance, and type 2 diabetes." (PMID 24444121, 2014).